RNU6-276P (RNA, U6 small nuclear 276, pseudogene)
Gene: Small nuclear RNA gene on chromosome 4 (55,798,636 to 55,798,731, forward strand). Ensembl gene ENSG00000251923.
Homologues: Orthologues: macaque U6 (92% identical), pig U6 (68% identical). Paralogues in human: RNU6-1209P (86% identical), RNU6-742P (86% identical), RNU6-797P (84% identical), RNU6-1181P (83% identical), RNU6-74P (83% identical), RNU6-767P (83% identical), RNU6-986P (83% identical), RNU6-106P (82% identical), RNU6-1145P (82% identical), RNU6-1316P (82% identical), RNU6-59P (82% identical), RNU6-633P (82% identical), and 1283 more.